VEGFA (vascular endothelial growth factor A)
Diseases named in the same sentence as VEGFA in open-access papers (continued):
Sharing a sentence is not in itself a finding about the gene and the disease.
bladder cancer (continued). "Exploring these hypotheses is crucial for understanding whether similar synergistic effects from the co-inhibition of PGF and VEGFA occur in other types of cancer, beyond bladder cancer, and warrants further investigation." (PMID 39628692, 2024). "However, VEGFA exhibits higher expression in pT1 bladder cancers than muscle-invasive (≥pT2) bladder cancers 22-24." (PMID 39628692, 2024). "VEGFA expression was also elevated in bladder cancer tissues." (PMID 37234708, 2023). "In previous studies, VEGFA could activate Ras/ERK signaling to promote bladder cancer cell proliferation, differentiation, and migration." (PMID 35173146, 2022). "Studies have shown that VEGFA can affect the infiltration of CD163+ TAM in bladder cancer, and the changes in VEGF receptor expression are linked to the disease staging and recurrence of bladder cancer." (PMID 36741702, 2022). "Similarly, circ0001429 was found to upregulate VEGFA expression by sponging miR-205-5p to promote the growth and metastasis of bladder cancer cells." (PMID 31973726, 2020). "Indeed, the angiogenic factor vascular endothelial growth factor-A (VEGF-A) is highly expressed both in tumor and urine samples of bladder cancer patients and correlates with poor prognosis, being associated with progression and tumor recurrence." (PMID 27879653, 2016). "No data are available about EA influence on bladder cancer cell invasion of the extracellular matrix triggered by vascular endothelial growth factor-A (VEGF-A), an angiogenic factor associated with disease progression and recurrence, and tumor growth in vivo." (PMID 27879653, 2016). "Taken together, our results indicate that KLF5 promotes angiogenesis of bladder cancer through directly regulating VEGFA transcription and suggest that KLF5 could be a novel therapeutic target for angiogenesis inhibition in bladder cancer." (PMID 26544730, 2015). "Taken together, our results suggest that KLF5 may play an important role in the angiogenesis of bladder cancer through regulating VEGFA." (PMID 26544730, 2015). "In addition, there was a positive correlation between KLF5 and VEGFA expression in human bladder cancer tissues by immunohistochemistry assay and statistical analysis from TCGA and GEO data." (PMID 26544730, 2015). "Importantly, KLF5 as well as VEGFA expression was positively correlated with neovascularization (as evaluated by CD31 staining) in bladder cancer tissues." (PMID 26544730, 2015). "Furthermore, METTL3 could regulate the expression of the TEK and VEGFA genes to promote angiogenesis and exacerbate bladder cancer progression." (PMID 36246403, 2022). "Thus, clinical evidence above supports that KLF5 might play roles in angiogenesis of human bladder cancer through regulating VEGFA expression." (PMID 26544730, 2015). "Moreover, at both mRNA level (TCGA and GEO data) and protein level (IHC staining), KLF5 and VEGFA were found to be co-expressed in human bladder cancer tissues, further supporting that KLF5 could be an essential regulator of VEGFA in bladder cancer." (PMID 26544730, 2015). "Furthermore, CID 5951923, a specific KLF5 transcriptional inhibitor identified by cell-based ultrahigh-throughput screening, abolished KLF5 and VEGFA expression in 5637 and WH bladder cancer cells, suggesting potential application of KLF5 inhibitor in bladder cancer treatment." (PMID 26544730, 2015). "Thus, inhibition of KLF5 could avoid the bypass of different pathways and it could be a better strategy to suppress VEGFA in bladder cancer." (PMID 26544730, 2015). "Growth factors (EGF and bFGF) and stimuli (PMA and LPA) that activated downstream oncogenic signaling (such as PKC, MEK/Erk and PI3K/Akt) could elevate the expression of KLF5, then increased VEGFA transcriptional efficiency and promoted bladder cancer angiogenesis." (PMID 26544730, 2015).
bladder cancer (continued). "Recent studies have shown that the infiltration of TANs increases the levels of VEGFA and MMP9 via the ERK/JNK pathway, facilitating lymphangiogenesis in bladder cancer." (PMID 40083688, 2025). "This process promotes the secretion of VEGFA and MMP9 by neutrophils, regulating lymphangiogenesis and thereby facilitating the lymphatic metastasis of bladder cancer." (PMID 40083688, 2025). "Mechanistically, transcription factor ETV4 enhances bladder cancer cells-derived CXCL1/8 to recruit TANs, increasing VEGFA and MMP9 secretion from TANs to promote lymphangiogenesis and lymphatic metastasis of bladder cancer." (PMID 39726782, 2024). "In bladder cancer (BCa), Wang and coworkers found that METTL3 ablation in BCa CSCs suppressed tumor angiogenesis by regulating TEK and VEGFA." (PMID 39691597, 2024). "We found that PGF promotes angiogenesis in bladder cancer in addition to VEGFA, and the combined inhibition of PGF and VEGFA yields synergistic effects in tumor growth inhibition and anti-tumor immunity." (PMID 39628692, 2024). "circRNA-MYLK was found to activate vascular endothelial growth factor A (VEGFA) through acting as a sponge of miR-29a, thereby promoting tumor growth, metastasis, and angiogenesis of bladder cancer." (PMID 33623789, 2021). "CircRNA-MYLK is an oncogene in bladder cancer, and it activates the VEGF-A/VEGFR-2 signaling pathway by functioning as a sponge for miR-29a to up-regulate VEGFA expression." (PMID 33777729, 2021). "These hub nodes such as VEGFA, EGFR, ESR1, PLG, and MAPK3 were mainly enriched in pathways like proteoglycans in cancer, bladder cancer, and estrogen-signaling pathway." (PMID 32256653, 2020). "Circular RNA MYLK regulates VEGFA/VEGFR2 signaling pathway and promotes cancer progression through serving as a ceRNA of miR-29a in bladder cancer." (PMID 32497020, 2020). "In bladder cancer, circRNA-MYLK served as miR-29a sponge and then activated VEGFA/VEGFR2 and downstream Ras/ERK signaling pathway, thereby promoting the proliferation, metastasis and epithelial-mesenchymal transition of bladder cancer cells." (PMID 32158357, 2020). "Zhong et al13 showed that circMYLK directly interacts with miR‐29a to modulate the VEGFA/VEGFR2 signalling pathway to promote the proliferation and metastasis of bladder cancer." (PMID 32342645, 2020). "In bladder cancer, circRNA-MYLK binds to miR-29a to target VEGFA, which normally activates its receptor VEGFR2 and the downstream Ras/ERK signaling pathway, contributing to tube formation and cytoskeletal rearrangement." (PMID 32943996, 2020). "Accordingly, we select the intersection of two gene sets, namely the bladder cancer and PI3K–Akt pathways, which then generates four common genes, EGF, EGFR, THBS1, and VEGFA (EntrezGene ID: 1950, 1956, 7057, 7422)." (PMID 30868054, 2019). "In bladder cancer tissue, the overexpression of HO-1 was correlated with the increased expression of Nrf2, HIF-1α, HIF-2α, and VEGFA." (PMID 31717324, 2019). "On the other hand, the protein levels of KLF5 and VEGFA are correlated with the expression of CD31, a marker of neovascularization, in human bladder cancer tissues and tumor xenografts in nude mice." (PMID 26544730, 2015). "Because VEGFA plays predominant roles in tumor angiogenesis, we decide to focus our investigation on the regulation of VEGFA by KLF5 and its roles in bladder cancer angiogenesis." (PMID 26544730, 2015). "We chose five candidate genes (PTPRF, MMP2, VEGFA, CDH1 and CLDN7) that were detected differential expression by Cuffdiff and involved in Bladder cancer pathway, cell adhesion molecules (CAMs) pathway and focal adhesion pathway." (PMID 24622401, 2014). "In conclusion, our data confirm the involvement of high VEGFA and OPN levels in bladder cancer, as well as an important role for FGF2 and RHOC in this disease." (PMID 22895562, 2012).
bladder cancer (continued). "VEGFA was the most sensitive (81.8%) factor and FGF2 the most specific (76.6%) one, for distinguishing bladder cancer patients from the control samples, with an AUC of 0.751 (95% CI, 0.674–0.817) and 0.742 (95% CI, 0.664–0.810), respectively." (PMID 22895562, 2012). "The VEGFA and OPN transcript levels were greater in the bladder cancer tissue than in the normal urothelium (P<0.001)." (PMID 22895562, 2012). "Ablation of METTL3 in bladder cancer stem cells suppresses TEK and VEGFA expression." (PMID 39691597, 2024). "Moreover, downregulation of CA9, NDRG1, SLC2A1, VEGFA, and upregulation of MDM2 were further verified in an additional bladder cancer cell line, 5637 cells." (PMID 38339062, 2024). "In bladder cancer, miR-195-5p as target of DLX6-AS1 was shown to down-regulate the vascular endothelial growth factor A (VEGFA) and consequently inhibit malignancy phenotype in cancer cells, while miR-195-5p inhibition returned the DLX6-AS1 tumorigenic effects." (PMID 35281110, 2022). "Studies have shown that circMYLK produced by human myosin light chain kinase (MYLK) can competitively bind to miR-29a, abolishing miR-29a inhibition of VEGFA/VEGFR2 and downstream Ras/ERK signaling pathways, thereby promoting epithelial-mesenchymal transition and bladder cancer development." (PMID 34786637, 2022). "A previous study has reported that miR-29b suppresses angiogenesis by targeting of MMP-2 and VEGFA, although restoration of miR-29b could inhibit the metastasis and reverse the EMT in bladder cancer." (PMID 33407520, 2021). "Therefore, four overlapping genes (EGF, EGFR, VEGFA, and THBS1) were extracted from the bladder cancer and PI3K–AKT pathways." (PMID 30868054, 2019). "In addition, circRNA-MYLK promotes cell proliferation, migration and invasion by directly binding to miR-29a and subsequently relieves suppression for target VEGFA, which activates VEGFA/VEGFR2 signaling pathway in bladder cancer." (PMID 31438963, 2019). "Furthermore, microarray data profiling of human bladder cancer tissues downloaded from TCGA and GEO database was applied to examine the co-expression of KLF5 and VEGFA." (PMID 26544730, 2015). "In the bladder cancer mouse model, the introduction of an anti- programmed cell death protein 1 (PD-1) therapeutic regimen combined with the targeted inhibition of PGF and VEGFA, led to a significantly elevated survival rate compared to the outcome observed with anti-PD-1 monotherapy." (PMID 39628692, 2024). "These hub nodes such as VEGFA and EGFR were mainly enriched in GO functions including positive regulation of MAP kinase activity, activation of protein kinase activity, regulation of MAP kinase activity, and pathways like proteoglycans in cancer, bladder cancer, and estrogen signaling." (PMID 32256653, 2020). "Interestingly, VEGFR2 could also act as the downstream driver gene of circRNA-MYLK when binding to miR-29a and relieving its suppression for VEGFA, and promote Ras/ERK signaling pathway in bladder cancer." (PMID 30819137, 2019).
proliferative diabetic retinopathy (219 papers, 2008 to 2026). Advanced retinopathy due to diabetes mellitus characterized by the formation of new vessels in the retina. "For example, miR-15b, which targets VEGFa mRNA, exhibits downregulation in the retinas of patients with proliferative diabetic retinopathy." (PMID 38997088, 2024). "Yaping found that VEGFA was highly upregulated in the T2D retina; it is a new potential therapeutic target and biomarker for proliferative diabetic retinopathy treatment and diagnosis." (PMID 37049846, 2023). "The single nucleotide mutation rs139876191 in HMGA1 can down-regulate expression of VEGFA and inhibit proliferative diabetic retinopathy." (PMID 34527669, 2021). "This study reports on the pathological significance of the vitreous fatty acid-binding protein (Vt-FABP) 4 and 5, and vascular endothelial growth factor A (Vt-VEGFA) in patients with retinal vascular diseases (RVDs) including proliferative diabetic retinopathy (PDR) and retinal vein occlusion (RVO)." (PMID 35454958, 2022). "Recently, the level of vascular endothelial growth factor A (VEGF-A) was found to be upregulated in the aqueous humor of NVG patients when compared with proliferative diabetic retinopathy subjects (1.2-fold), indicating specific glaucomatous inflammation, different to secondary retinopathy." (PMID 34439995, 2021). "MITF, a master regulator of the RPE differentiation and homeostasis, was footprinted on VEGFB proximal promoter (−2, TSS) and VEGFA, with major clinical relevance in neovascular AMD and proliferative diabetic retinopathy." (PMID 40565279, 2025). "In proliferative diabetic retinopathy fibrovascular membranes (GSE94019), HRI elevation in normal versus diabetic endothelial (p = 0.0702) paralleled trends in ATF4 and VEGFA, implicating HRI as a conserved node in metabolic stress responses." (PMID 41010531, 2025).
liver cancer (209 papers, 2010 to 2026). An epithelial or non-epithelial malignant neoplasm that arises from the liver. "Increased VEGFA is associated with liver cancer development, and several reports have indicated that VEGFA inhibition can extremely block the malignant behaviors of the cancer cells." (PMID 36193503, 2022). "However, the roles and underlying mechanisms of amarogentin in inhibiting VEGFA-induced angiogenesis in residual liver cancer after iRFA treatment are poorly understood." (PMID 33145353, 2020). "The miR-138-5p miRNA can suppress the vascular simulation of HepG2 and Hep3B cells via inhibition of the HIF-1α/VEGFA cascade in liver cancer." (PMID 39596660, 2024). "Some studies have found that BMP9-ID1 can activate the expression of HIF-1α and VEGFA in the blood supply of liver cancer, which provides a new strategy for targeted liver cancer therapies." (PMID 39619441, 2024). "VEGFA, as the major pro-angiogenetic molecule, is induced by thyroid hormone, thereby accelerating angiogenesis and metastasis of liver cancer." (PMID 37854285, 2023). "In comparison with the blank group, LFE regulated the mRNA expression levels of PTEN, PI3K, AKT, PDCD4, VEGFA, Caspase 9, Caspase 3, Bcl-2, Bax and Bad in liver cancer cells to different degrees." (PMID 36110518, 2022). "Compared with the blank group, LFE regulated the proteins expression levels of PTEN, PI3K, p-PI3K, Akt, p-Akt, VEGFA and Caspase 9 in liver cancer cells to different degrees." (PMID 36110518, 2022). "Knockdown of OIP5-AS1 repressed proliferation and migration via regulating miR-3163/VEGFA axis in liver cancer cells." (PMID 35756672, 2022). "The new regulatory data with miR-637 in liver cancer have an importance for characterization in the databases, being a potential biomarker for VEGFA." (PMID 35205327, 2022). "Studies have reported that cancers with high levels of VEGFA are particularly sensitive to VEGFA inhibition, and these include liver cancer, sarcoma, and breast cancer." (PMID 33099574, 2020). "The mRNA and protein expression levels of CD133 and VEGFA were significantly higher in the residual liver cancer tissue than in the liver cancer tissues treated by hepatectomy." (PMID 33145353, 2020). "The interleukin, β and α, respectively, supported angiogenesis by upregulating VEGFA also in breast and liver cancer cells." (PMID 33020452, 2020). "The number of liver cancer stem cells (LCSCs) and the level of vascular endothelial growth factor A (VEGFA) were assessed in liver cancer tissue after iRFA." (PMID 33145353, 2020). "In cancers, high expression of VEGFA was particularly related to high sensitivity to VEGFA inhibition treatment, and these cancers included liver cancer, sarcoma, and breast cancer." (PMID 33099574, 2020). "The mRNA levels of KLF8 and VEGFA in the same liver cancer samples were detected by qPCR, and the relative Ct values for KLF8 and VEGFA were 8.29 ± 2.01 and 4.63 ± 1.32, respectively." (PMID 30479372, 2018). "As a novel promoter of tumor angiogenesis, VEGFA was reported to be a direct target of miR-497 in liver cancer." (PMID 27015364, 2016). "Additionally, we analysed the expression of VEGFA protein in liver cancer tissue and adjacent tissue." (PMID 36729917, 2023). "Similarly, Scutellarein, a flavone present in S. lateriflora, reduces oxidative stress and suppresses the development of liver cancer by impairing the expression of VEGFA, Flt-1, HIF-1α, MMP2, and MMP9." (PMID 34639131, 2021).